SNORA70H (small nucleolar RNA, H/ACA box 70H)
Gene: Small nucleolar RNA gene on chromosome 1 (201,978,461 to 201,978,595, forward strand). Ensembl gene ENSG00000206637.
Gene Ontology:
Biological process: RNA processing
Cellular component: nucleolus
Homologues: Orthologues: chimpanzee SNORA70 (100% identical), macaque SNORA70 (96% identical). Paralogues in human: SNORA70G (96% identical), SNORA70B (94% identical), SNORA70J (94% identical), SNORA70 (93% identical), SNORA70C (93% identical), SNORA70I (92% identical), SNORA70 (90% identical), SNORA70E (90% identical), SNORA70D (88% identical), SNORA70 (87% identical), SNORA70F (87% identical), SNORA70 (84% identical), and 12 more.